DKK1 (dickkopf Wnt signaling pathway inhibitor 1)
Diseases named in the same sentence as DKK1 in open-access papers (continued):
Sharing a sentence is not in itself a finding about the gene and the disease.
femoral neck fracture (2 papers, 2022 to 2023). Fractures of the short, constricted portion of the thigh bone between the femur head and the trochanters. "Western blot was applied to detect the level of DKK‐1 protein expression in hip joint capsule tissues from four patients with AS as well as four patients with femoral neck fracture (FNF) caused by trauma as control." (PMID 37506134, 2023). "In postmenopausal women with a previous fragility fracture and in elderly women with a recent femoral neck fracture, a positive correlation between protein DKK1 levels in the bone and BMD was detected." (PMID 36552348, 2022).
fetal growth restriction (2 papers, 2018 to 2024). A fetus that does not grow beyond the 10th percentile of conventionally accepted weight for gestational age. "DKK-1 is a known inhibitor of the Wnt signaling pathway, which is involved in a wide range of processes and has been linked to immunosuppressive effects and fibrosis, and has been shown to be decreased during fetal growth restriction." (PMID 38920640, 2024).
hyperphosphatemia (2 papers, 2019 to 2021). Abnormally high level of phosphate in the blood. "WNT/β-catenin pathway inhibitors such as Dickkopf-related protein 1 (DKK1) or secreted frizzled-related proteins (SFRPs) showed anti-calcific effects in VSMCs during in vitro hyperphosphatemia." (PMID 30887097, 2019). "This could be due to increased extraosseous production of sclerostin and Dkk-1 and hyperphosphatemia, increased calcitonin exposure, and absent renal clearance of both molecules." (PMID 34603797, 2021).
hyperthyroidism (2 papers, 2022). Overactivity of the thyroid gland resulting in overproduction of thyroid hormone and increased metabolic rate. "The importance of DKK1 for bone homeostasis is also highlighted by the findings that loss of DKK1 partially reduces altered bone volume associated with hypo- as well as hyperthyroidism and significantly reduces alveolar bone loss in mice with experimentally induced periodonditis." (PMID 36552348, 2022). "In a study published by the same group of researchers, the role of DKK1 in hyperthyroidism-induced bone abnormalities in mice with global or osteocyte-specific DKK1 deletion was investigated." (PMID 36005583, 2022). "Our results regarding the behavior of sclerostin and DKK1 serum concentrations in hyperthyroidism are consistent with earlier findings." (PMID 36005583, 2022). "Another explanation is that they complement each other, with the canonical Wnt pathway increasing sclerostin and decreasing DKK1 expression in hyperthyroidism to avoid excessive osteoblast differentiation." (PMID 36005583, 2022). "In neither of these groups, loss of DKK1 function was not sufficient to fully reverse bone changes caused by hyperthyroidism." (PMID 36005583, 2022). "Still, postnatal deletion of DKK1 in mice did not reverse bone tissue changes induced by hyperthyroidism." (PMID 36005583, 2022).
hypoglycaemia (2 papers, 2024 to 2025). "With severe hypoglycemia, the study controls showed an increase in Angiopoietin 1 (ANGPT1) (p < 0.01) and Dickkopf-1 (DKK1) (p < 0.01), but no changes were seen with mild hypoglycemia." (PMID 38927344, 2024). "Following hypoglycemia, transient changes from baseline occurred in DKK1, cathepsin A, cathepsin G, cathepsin H, cathepsin S, cathepsin Z, parathyroid hormone (PTH), Sphingosine kinase 1 and 2 (SPK1/2), and interleukin-1 beta (IL1 beta) over the post-hypoglycaemia time course." (PMID 41373586, 2025).
inflammatory bowel disease (2 papers, 2017 to 2021). A spectrum of small and large bowel inflammatory diseases of unknown etiology. "Previous studies revealed that DKK1 played a role in promoting the development and differentiation of immunocytes which actively participates in the progression of inflammatory bowel disease." (PMID 34090510, 2021). "Furthermore, TLR4 possibly activate down-stream JAK/STAT pathway to secrete IL-17A in inflammatory bowel disease, which suppressed WNT pathway through stimulating DKK1 in intestinal stem cells." (PMID 29228588, 2017). "Relying on competing with Wnt ligands for LRP5/6 receptors, DKK1 has a role in promoting the development and differentiation of immunocytes, such as macrophages, DCs, and CD4+ T cells, which actively participates in the progression of inflammatory bowel disease." (PMID 34090510, 2021).
injury (2 papers, 2015 to 2020). Damage inflicted on the body as the direct or indirect result of an external force, with or without disruption of structural continuity. "Up to date, there have been many experimental studies detecting increased expression of DKK‐1 in brain tissues with acute brain injury." (PMID 32324340, 2020).
joint diseases (2 papers, 2010). "Previous reports have demonstrated that increased Dkk-1 levels were correlated with the pathogenesis of joint disorders." (PMID 21062498, 2010).
juvenile osteoporosis (2 papers, 2018 to 2020). "The adult patient harboring only a DKK1 variant had a mild phenotype, in contrast to the female patient with severe juvenile osteoporosis with a combination of LRP5 and DKK1 variants, so the combination of two variants in the same pathway may accentuate the phenotype." (PMID 30283887, 2018).
kidney damage (2 papers, 2016 to 2023). "We further investigated whether PMWCNT-induced kidney damage could affect bone mineral metabolism and vascular calcification, which are major categories of aging, using related serum proteins including DKK-1, FGF-23, and sclerostin." (PMID 37112600, 2023). "Herein, we confirmed that plasma from diabetic patients with nephropathy promotes podocyte apoptosis, as assessed by cleaved caspase 3 and TUNEL assay, likely due to an increased concentration of plasma DKK-1." (PMID 27320846, 2016).
kidney transplant (2 papers, 2018 to 2025). A surgical procedure in which one or both kidneys from a donor are implanted into a recipient. "Nevertheless, there remains insufficient information regarding how CKAP4 and DKK1 interact during kidney transplant rejection." (PMID 40922300, 2025).
migraine (2 papers, 2022 to 2025). "The LCV analyses found a significant genetic causality on migraine for higher levels of two blood proteins, DKK1 and PDGFB." (PMID 35546551, 2022). "Our finding of a strong causal effect of higher levels of DKK1 (GCP = 0.88) on migraine risk might be linked to the dysfunction of Wnt signalling and CAA." (PMID 35546551, 2022). "The risk-increasing effect of DKK1 is particularly interesting—indicating a role for downregulation of β-catenin-dependent Wnt signalling in migraine risk, suggesting Wnt activators that restore Wnt/β-catenin signalling in brain could represent therapeutic tools against migraine." (PMID 35546551, 2022). "Lastly, our scan for inferring causality identified five blood proteins (DKK1, PDGFB, GSTA4, FARS2 and CHIC2) with a significant genetic causality on migraine." (PMID 35546551, 2022). "We also noted that DKK1 and CALCA—which encodes CGRP, a migraine-specific drug target—have a similar pattern of RNA expression across ten HPA brain regions with a high expression in “Pons and Medulla oblongata” that is a part of the brain stem." (PMID 35546551, 2022). "We show that higher levels of DKK1 and PDGFB, and lower levels of FARS2, GSTA4 and CHIC2 proteins have a significant causal effect on migraine." (PMID 35546551, 2022). "In addition, we identified that higher levels of DKK1 and PDGFB, and lower levels of FARS2, GSTA4 and CHIC2 causally increase the risk of migraine." (PMID 35546551, 2022). "Taken together, our current results suggest DKK1 and PDGFB as two promising therapeutic targets against migraine." (PMID 35546551, 2022). "Therefore, as proposed for AD, Wnt activators that restore Wnt/β-catenin signalling in brain, particularly those targeting Wnt antagonist DKK1 and Wnt receptor LRP6, could represent novel therapeutic tools for migraine treatment." (PMID 35546551, 2022).
mineral bone disorder (2 papers, 2019 to 2022). "The discovery of Wnt inhibitors, among them Dickkopf-related protein 1 (Dkk-1), released during renal repair as crucial components of mineral bone disorder (MBD) pathogenesis, suggests that additional pathogenic factors need to be explored." (PMID 31687048, 2019). "Since the roles of sclerostin and DKK1 in mineral bone disorders remain inconclusive and the relationship between serum sclerostin and DKK1 with BMD in HD patients is controversial, the aim of this study was to examine the association of sclerostin and DKK1 with lumbar BMD in HD patients." (PMID 35334561, 2022).
neuroendocrine tumor (2 papers, 2020 to 2021). "TNC also promotes stromal events such as the angiogenic switch and the formation of more but leaky blood vessels involving Wnt signaling and inhibition of Dickkopf1 (DKK1) in a neuroendocrine tumor model." (PMID 32817625, 2020). "Tnc has also been shown to downregulate the Wnt inhibitor Dkk-1 in a neuroendocrine tumor model." (PMID 34434963, 2021).
oral squamous cell carcinoma (2 papers, 2015 to 2025). "The purpose of this study is to determine the roles of genes DKK1, HOXC6, and YKT6 in biopsy-proven oral squamous cell carcinomas and to correlate tumour severity with gene expression levels." (PMID 41477365, 2025). "In the first stage, 16 oral squamous cell carcinoma cell lines were screened for the methylation of DACH1, DKK1, LKB1, PPP2R2B, RUNX3, SFRP2, and WIF-1 using methylation-specific PCR." (PMID 25487617, 2015). "Based on these results, we identified DACH1, DKK1, and WIF-1 as potential epimarkers in OSCC and further analyzed their methylation in a group of oral squamous cell carcinoma patients." (PMID 25487617, 2015). "The methylation of DACH1, DKK1, LKB1, PPP2R2B, RUNX3, SFRP2, and WIF-1 was analyzed in 16 oral squamous cell carcinoma cell lines using the methylation-specific polymerase chain reaction." (PMID 25487617, 2015).
osteonecrosis (2 papers, 2017 to 2022). A none disease characterized by death of bone tissue due to a lack of blood supply. "Consistently, in the present study, the serum secretion of DKK1 considerably increased after osteonecrosis induction and effectively decreased after PDTC treatment." (PMID 28931847, 2017). "Interestingly, increased DKK-1 mediates the impaired osteogenic capacity of adipose tissue-derived MSCs in steroid-induced osteonecrosis." (PMID 35462544, 2022).
Pagets disease of bone (2 papers, 2016 to 2019). "In the adult, DKK-1 is implicated in bone formation and bone disease, particularly multiple myeloma and Pagets disease of bone." (PMID 27049730, 2016). "This may also be complementary to prior discoveries that increased DKK-1 production- and thus an inhibition of Wnt- allows proliferation of mesenchymal stem cells and is noted in Paget's disease of bone." (PMID 27049730, 2016).
Parkinson's (2 papers, 2018 to 2023). "In Parkinson's disease (PD), strong GSK-3β activity and low Wnt/β-catenin signaling are correlated with high DKK1 expression." (PMID 37780577, 2023).
Peri-Implantitis (2 papers, 2014 to 2019). An inflammatory process with loss of supporting bone in the tissues surrounding functioning DENTAL IMPLANTS. "However, when evaluating genetic markers for peri-implantitis clinically, no direct relation of DKK-1 and peri-implantitis is seen (Hallet al., 2011)." (PMID 31031968, 2019). "A differentiation of peri-implantitis to other inflammatory periodontal processes cannot be made on the basis of human saliva by markers such as osteocalcin, tartrate-resistant acid phosphatase (TRAP), dickkopf-related protein-1 (DKK-1), osteoprotegerin (OPG) and cathepsin K (CatK)." (PMID 25185675, 2014).
periodontal diseases (2 papers, 2017 to 2019). "The here presented literature supports the significant effects of SOST and DKK-1 in the periodontium system and periodontal diseases." (PMID 31031968, 2019).
pneumonia (2 papers, 2022 to 2023). An acute, acute and chronic, or chronic inflammation focally or diffusely affecting the lung parenchyma, caused by an infection in one or both of the lungs (by bacteria, viruses, fungi, or mycoplasma.). "Our study identified multiple genetic DKK1 variants associated with increased cytokine production in humans and DKK1 serum levels were highly variable in our cohort of patients with pneumonia." (PMID 36539532, 2022). "Circulating DKK1 levels during the acute, initial phase of pneumonia (day 1 or 2 of hospitalization) were characterized by considerable interindividual variability (range: 1.13–48.05 pmol/l)." (PMID 36539532, 2022).
prostate adenocarcinoma (2 papers, 2021 to 2024). "However, DKK1 expression was significantly decreased in bladder urothelial carcinoma (BLCA), kidney chromophobe (KICH), kidney renal papillary cell carcinoma (KIRP), and prostate adenocarcinoma (PRAD)." (PMID 34899842, 2021).
retinal ischemia (2 papers, 2025). A ischemic disease that involves the retina. "Intravitreous injections of catalpol (0.5 or 0.25 mM), Wnt inhibitor DKK1 (1 μg/4 μL), anti-VEGF Lucentis (40 μg/4 μL), or anti-VEGF Eylea (160 μg/4 μL) were administered to the rats’ eyes 15 min before or after retinal ischemia." (PMID 40362263, 2025).
sarcopenia (2 papers, 2019 to 2023). Progressive decline in muscle mass due to aging which results in decreased functional capacity of muscles. "Biomarkers in the Wnt signaling pathway which is correlated with sarcopenia were also reported in one study, including the Dkk-1, Dkk-3, and SREBP1 biomarkers." (PMID 37349622, 2023). "Finally, administration of verteporfin improved muscle atrophy in (P)RR‐Tg mice via direct inhibition of YAP signaling, without affecting ABC and endogenous DKK1, whereas in aged WT mice, administration of verteporfin suppressed the expression of sarcopenia‐related genes." (PMID 31282603, 2019).
schizophrenia (2 papers, 2013 to 2023). A major psychotic disorder characterized by abnormalities in the perception or expression of reality. "Dkk1 is encoded by the DKK1 gene, which maps on chromosome 10 region q11.2, a region with linkage evidence for schizophrenia." (PMID 24403877, 2013). "It has been reported that plasma levels of soluble dickkopf 1 (DKK-1) and sclerostin are significantly lower in schizophrenia than in healthy controls." (PMID 36680208, 2023).
tongue squamous cell carcinoma (2 papers, 2017 to 2021). A squamous cell carcinoma that arises from the tongue. "Generally, miR-373-3p acts as a potent proto-oncogenic factor in tongue squamous cell carcinoma (TSCC), and upregulation of miR-373-3p leads to the promotion of TSCC invasion via activation of Wnt signaling by the downregulation of Dickkopf-1 (DKK1)." (PMID 34200891, 2021).
tooth agenesis (2 papers, 2021 to 2023). A tooth disease characterized by failure to develop one or more missing teeth. "This novel SATB2 variant inhibited osteo/odontogenesis of hDPSCs through Wnt/β-catenin signaling pathway by regulating DKK1 and histone demethylase JHDM1D, thus leading to the phenotype of tooth agenesis in the SAS patient." (PMID 34863303, 2021).
Ureteral obstruction (2 papers, 2011 to 2023). Obstruction of the flow of urine through the ureter. "Variation in expression profiles of many Wnt ligands, FZD receptors and β-catenin have been reported in the unilateral ureteral obstruction (UUO) mouse model of renal injury and reduction in interstitial injury identified in response to dickkopf homolog 1 (DKK-1), a Wnt signalling antagonist." (PMID 21876774, 2011).
urothelial carcinoma (2 papers, 2023 to 2025). A malignant neoplasm derived from the transitional epithelium of the urinary tract (urinary bladder, ureter, urethra, or renal pelvis). "This may explain why in a previous study, muscle invasive and high-grade urothelial carcinoma patients had higher DKK1 serum levels as compared to controls." (PMID 37086261, 2023).
acromegaly (1 paper, 2022). Acromegaly is an acquired disorder related to excessive production of growth hormone (GH) and characterized by progressive somatic disfigurement (mainly involving the face and extremities) and systemic manifestations. "High DKK-1 levels have been already reported in patients with acromegaly, and some studies describe an increase of this marker in patients with GH deficiency following GH replacement therapy." (PMID 36362602, 2022). "As concerns the role of RANK/RANK-L/OPG and DKK-1/sclerostin systems in acromegaly, many aspects remain to be clarified." (PMID 36362602, 2022).
age-related macular degeneration (1 paper, 2017). Age-related loss of vision in the central portion of the retina (macula), secondary to retinal degeneration. "Here, we investigated whether circulating levels of Dickkopf-1 (DKK-1), a specific inhibitor of this pathway, are altered in patients with exudative age-related macular degeneration (AMD)." (PMID 28455497, 2017).
alcoholic hepatitis (1 paper, 2019). Acute hepatitis resulting from ingestion of alcohol. "ChIP sequencing confirmed a gain in H3K27me3 at the promoter region of peroxisome proliferator-activated receptor γ and Dickkopf-1 (DKK1) in patients with alcoholic hepatitis as compared with healthy controls." (PMID 30539787, 2019).
allergic asthma (1 paper, 2021). A asthma with a basis in a pathological type I hypersensitivity reaction. "Activated platelets secrete IL-33, Dkk-1, and 5-HT or overexpress CD40L on the cell surfaces to induce Type 2 immune response or interact with TSLP-stimulated myeloid DCs through the RANK-RANKL-dependent manner to tune the sensitization stage of allergic asthma." (PMID 34440807, 2021).
anorectal malformation (1 paper, 2025). "A heterozygous DKK1 variant has been reported in an individual with anorectal malformation and hypospadias." (PMID 40037090, 2025).
aortic valve disease (1 paper, 2015). "Our results suggest that it might be interesting for further research examining the potential impact of Dkk-1 antagonists on progression of calcified aortic valve disease." (PMID 25889943, 2015).
arteriosclerosis (1 paper, 2024). A vascular disorder characterized by thickening and hardening of the walls of the arteries. "In contrast, some studies have linked increased DKK-1 levels with myocardial perfusion defects and Gal-3 levels with subclinical arteriosclerosis in patients with RA." (PMID 39337398, 2024).
astrocytomas (1 paper, 2021). "Our findings on 50 astrocytoma samples revealed promoter methylation of DKK1 in 38% and DKK3 in 42.86% of the samples." (PMID 34064046, 2021). "Our findings on DKK1 and DKK3 show the importance of methylation in the regulation of Wnt signaling activity and also indicate pro-oncogenic effects of GSK3β on astrocytoma development and progression." (PMID 34064046, 2021). "In the present study, we investigated genetic and epigenetic changes and protein expression levels of negative regulators of Wnt signaling, DKK1, DKK3, and APC as well as glycogen synthase kinase 3 (GSK3β) and β-catenin in 64 human astrocytomas of grades II–IV." (PMID 34064046, 2021). "In this study, 64 astrocytoma samples of grades II–IV were analyzed for genetic and epigenetic changes as well as protein expression patterns in order to explore the roles of the Wnt pathway components, such as DKK1, DKK3, GSK3β, β-catenin, and APC in astrocytoma initiation and progression." (PMID 34064046, 2021).
benign skin tumor (1 paper, 2022). "Keloid is benign skin tumor; therefore, it can be inferred that DKK1 is present at a low level in keloid, which was also confirmed by our previous data analysis and experimental detection." (PMID 35967426, 2022).
bile duct cancer (1 paper, 2022). "Prognostic value of CD8, β-catenin, and DKK1 expression in bile duct cancer." (PMID 35121803, 2022).